Y_RNA (Y RNA )
Gene: Miscellaneous RNA gene on chromosome 3 (61,739,127 to 61,739,229, reverse strand). Ensembl gene ENSG00000252420.
Homologues: Orthologues: chimpanzee Y_RNA (78% identical). Paralogues in human: Y_RNA (78% identical), Y_RNA (77% identical), RNY3 (76% identical), Y_RNA (76% identical), Y_RNA (75% identical), Y_RNA (74% identical), RNY3P1 (73% identical), RNY3P4 (73% identical), Y_RNA (73% identical), RNY3P12 (72% identical), RNY3P16 (72% identical), RNY3P5 (72% identical), and 90 more.